BCL3 (BCL3 transcription coactivator)
Diseases named in the same sentence as BCL3 in open-access papers (continued):
Sharing a sentence is not in itself a finding about the gene and the disease.
tumor (continued). "The combined knockdown of BCL3 and TNFα blocked this increase, suggesting the ‘tumour initiating phenotype” of suppressed BCL3 was mediated by TNFα." (PMID 38195591, 2024). "On the other hand, Bcl3 overexpression has been shown to promote tumour establishment and growth in ER-positive MCF-7 xenografts, while recently a small-molecule inhibitor of Bcl3 has shown efficacy in reducing tumour growth in triple-negative xenografts." (PMID 38255248, 2024). "Recently, a small-molecule Bcl3 inhibitor was shown to significantly inhibit TNBC tumour growth in vivo through the induction of apoptosis." (PMID 38255248, 2024). "Metastatic ErbB2 (HER2) tumour burden was reduced by 75% in BCL3-null mice and this was recapitulated in allografts of BCL3-null tumour cells into wild-type recipient mice, confirming the tumour cell autonomous effects of BCL3 on the metastatic process." (PMID 38195591, 2024). "Although the role of Bcl3 in tumor pathology is poorly understood, it mediates transcription suppression of NF-kB signaling and affects metastasis-associated genes." (PMID 35388653, 2022). "Given the reduced Bcl-2 protein and increased expression of Puma in bcl-3−/− tumors, Bcl-3 likely contributes to tumor cell survival, in part, through the activation and repression of these genes, respectively." (PMID 35681213, 2022). "This builds on previous work that has characterised a role for BCL-3 in promoting tumour survival, inhibiting apoptosis through the AKT pathway, HDM2 and DNA-PK." (PMID 35468497, 2022). "In this study, we have investigated the role of Bcl-3 in the normal mammary gland and impact on tumor pathology." (PMID 35681213, 2022). "Only one published study has proved that in the mouse xenograft model, BCL3 inhibited tumor growth via positively regulating STAT3/p-STAT3 and the downstream targets including cyclin D1." (PMID 35488886, 2022). "Here, we observed a specific staining of BCL3 in tumor cells in both, the cytoplasmic and nuclear compartment but this varied between the specimens." (PMID 35020071, 2022). "One proposed explanation for this phenomenon is the interaction of the tumor cells with cells of the tumor microenvironment via the Insulin-like growth factor RNA binding protein 5/B-cell lymphoma 3 (IGFBP5/BCL3) axis." (PMID 35020071, 2022). "Bcl-3 clearly has a role in regulating invasion and has been proposed as a target for prevention of tumor metastasis." (PMID 35681213, 2022). "Our observation that BCL3 staining is present in cytosol and nucleus in varying amounts, suggests a functional difference of BCL3 in these tumor cells, especially a different activation status of the protein." (PMID 35020071, 2022). "First of all, our study showed that hepatic SASP-activated macrophages depend on Bcl3, which contributes to establishing a tumor-promoting microenvironment and indicates a novel role for Bcl3 in senescent hepatocytes." (PMID 34530917, 2021). "The nuclear expression levels of BCL10, BCL3, and NF-κB (p65) in tumor cells were also downregulated in shBCL10-transfected PANC-1 group when compared with scrambled PANC-1 group." (PMID 34412631, 2021). "Previous studies reported the overexpression of PIR in different neoplastic transformation and its role in the enhancement of tumor formation due to inducing the expression of Bcl3 by forming the ternary complex with proto-oncogenes Bcl3 and NF-kB." (PMID 34262943, 2021). "In the present study, we also observed a positive correlation between IL6 expression in tumors and BCL3 expression in tumor-adjacent samples of ESCC patients, suggesting a possible dysregulation of this axis in the early stages of esophageal carcinogenesis." (PMID 34422669, 2021). "The predicted activities of motifs associated with EPAS, BCL3, FOXM1, and TBL1XR1 were higher in ILC than in the non‐ILC tumor cells." (PMID 33616307, 2021).
tumor (continued). "In both non-tumour and tumour cells, BCL-3 binds to processed p50 and p52 homodimers to activate or repress a subset of NF-κB regulated genes." (PMID 31930327, 2020). "(D) Relative mRNA expression levels of Cd14, Bcl3, Osmr and Nfkbia between the sorted Neu tumor sub-populations." (PMID 32840210, 2020). "Consistent with our previous observation, a significantly positive correlation between Bcl-3 and Ac-K49-β-catenin was found in the tumor specimens." (PMID 32355204, 2020). "(A) t-SNE plots showing the expression levels of Cd14, Bcl3, Osmr and Nfkbia in the Neu tumor sub-clusters." (PMID 32840210, 2020). "Apart from that, MCPIP1 is recognized as a tumor suppressor due to its induction of apoptosis of tumor cells, for instance by selectively enhancing mRNA decay of antiapoptotic gene transcripts, including Bcl2L1, Bcl2A1, RelB, Birc3, and Bcl3." (PMID 31651935, 2019). "BCL3 protein expression alters the transcriptomic and epigenetic signatures of tumor cells via the NF-κB pathway and changes the tumor microenvironment by inducing the secretion of cytokines." (PMID 31754093, 2019). "The BCL-3 protein is highly expressed in a subset of CRCs, in which we have recently shown that it inhibits apoptosis and promotes tumour growth." (PMID 30792270, 2019). "BCL-3 bears numerous tumour-promoting capabilities, such as increasing proliferation and inflammation, inhibiting apoptosis, and promoting metastasis." (PMID 30792270, 2019). "Increased p50 and Bcl-3 co-expression in tumours compared to adjacent tissue has also been described." (PMID 30205516, 2018). "In patients undergoing liver resection for HCC, increased levels of NF-κB p50 homodimers and Bcl-3 were observed in the resected tumor, providing first evidence for its role in hepatocarcinogenesis." (PMID 28915576, 2017). "In summary, hepatocyte-restricted Bcl-3 overexpression reduced hepatocarcinogenesis related to prolonged liver injury early after tumor initiation likely due to decreased survival of DEN/PB-damaged, premalignant cells." (PMID 28915576, 2017). "CYLD (ubiquitin carboxyl-terminal hydrolase cyclindromatosis), another well-established tumour suppressor, plays a protective role during G1 via the transcription factor BCL-3 (B-cell lymphoma 3 protein)." (PMID 28900014, 2017). "Here we establish that BCL-3 is a potent survival factor in colorectal carcinogenesis, particularly in the context of stresses related to the tumour microenvironment." (PMID 26033966, 2016). "Reduced expression of cyclin D1/N-cadherin in residual tumors coupled with static tumor growth confirmed the importance of p50/Bcl3 in the growth of BCCs in our Ptch1+/−/SKH-1 mice." (PMID 26413810, 2015). "Next, immunohistochemical staining of Bcl-3 was performed in tumours from a patient cohort of 270 CRC patients." (PMID 25929479, 2015). "Staining of freshly isolated tumour tissue using an antibody against Bcl-3 with corresponding blocking peptide in a concentration ratio 1:5 demonstrated the specificity of Bcl-3 antibody for immunohistochemistry staining." (PMID 25929479, 2015). "In 92% of the normal samples 76–100% of all nuclei were positive for Bcl-3 compared to only 33% of the tumour samples." (PMID 25929479, 2015). "We next investigated the associations between the nuclear fraction of Bcl-3 positive cells and clinicopathological parameters in the CRC tumours." (PMID 25929479, 2015). "The BCL3 gene is located at chromosome 19, a chromosome with frequent trisomy in MM patients having a hyperdiploid tumor." (PMID 19191868, 2009). "DNA methylation analysis assigned 77% (51/66) of patients with IGH::BCL3-translocation with at least 60% tumor cell content to the naive B-cell-like group but unraveled a distinct and during follow-up stable signature resembling in part plasma cell-like epigenetic features." (PMID 42064384, 2026).
tumor (continued). "In addition to immune suppression and advanced tumour stages, the study identified directly correlating variables related to elevations in BCL3 expression." (PMID 40486320, 2025). "BCL3 may help tumours survive and progress towards malignancy by suppressing immune cells that are in charge of removing tumours." (PMID 40486320, 2025). "Furthermore, the classification by tumour stage revealed that BCL3 expression was consistently elevated in Stage IV cases compared to Stage III, particularly in SCC patients." (PMID 40486320, 2025). "Consequently, BCL3 appeared to put a modulatory force on the immunity environment of tumours in OC, particularly in SCC cases." (PMID 40486320, 2025). "Similarly, there are several studies demonstrating a direct role for BCL3 in promoting tumour cell survival, which impacts on tumour growth and viability, yet often the precise mechanism of action of BCL3 remains elusive." (PMID 38195591, 2024). "Interestingly, Pim3, Bcl3 and Inhbb were upregulated in ECs isolated from the lungs and liver 14 d after tumor cell inoculation, a time point where CTCs were present, as indicated by the liver metastases." (PMID 39627185, 2024). "After MWA, tumor-promoting genes such as BCL3, Myh10, NR6A1, and PFKFB3 displayed downregulation." (PMID 38779358, 2024). "Given the relationship between BCL-3 expression levels in CRC and poor patient prognosis, we sought to investigate whether BCL-3 plays a role here by altering tumour response to therapeutic agents." (PMID 35468497, 2022). "At this stage, BCL3 might be activated intrinsically or by interactions with the tumor micro-environment." (PMID 35020071, 2022). "Given the poor outcome of patients with high BCL-3 expressing tumours and its previously characterised function in enhancing tumour cell survival, we hypothesised that BCL-3 expression may determine therapeutic resistance of tumours." (PMID 35468497, 2022). "In this context, BCL3 overexpression in the normal-appearing tumor-surrounding tissue observed in this study could represent one of these predisposing molecular alterations." (PMID 34422669, 2021). "Moreover, using the proposed cut-off for mRNA analysis, BCL3 overexpression was consistent in non-tumor adjacent tissues and tumors in the spatial intratumoral analysis, showing its robust potential as a biomarker of diagnosis." (PMID 34422669, 2021). "Bcl-3 depletion significantly suppressed xenograft tumor growth and tumorigenic cell frequency." (PMID 32355204, 2020). "Furthermore, oncogenic properties of the LINC00176/BCL3/CP axis were also demonstrated by tumour formation in vivo generated upon injecting cells in nude mice." (PMID 31668012, 2020). "In addition to MYC, many tumor-associated genes such as RUNX1, FOSL2, BCL3 and ID2 are driven by SEs in diverse tumor types." (PMID 33628735, 2020). "Importantly, this work has begun to shed light on our mechanistic understanding of the function of BCL-3 in tumour promotion and progression." (PMID 31930327, 2020). "The effect of BCL-3 on tumour growth/proliferation has been observed in different tumour types." (PMID 31930327, 2020). "Data from this study suggest that BCL-3 may play a role in the de-differentiation and reconstitution of the tumour." (PMID 30792270, 2019). "Importantly, to verify where p50:p50:Bcl3 complexes truly function as tumour promoters in-depth molecular analysis such as EMSA, nuclear localisation, IP and analysis of other NF-κB subunits should be included." (PMID 30205516, 2018). "Bcl-3 reduced the number and especially the size of tumor nodules." (PMID 28915576, 2017). "It is tempting to speculate, that Bcl-3 overexpression induces cell death in oncogenic foci and transformed hepatocytes early during hepatocarcinogenesis, thus resulting in reduced tumor burden." (PMID 28915576, 2017).
tumor (continued). "Finally, we make the interesting observation that the common NSAID 5-ASA can suppress BCL-3 expression in the tumour cells." (PMID 26033966, 2016). "Given the importance of AKT as a potent survival factor in colorectal carcinogenesis, we addressed whether BCL-3 activated the AKT/PKB signalling pathway in the tumour cells." (PMID 26033966, 2016). "Importantly, the reduced lung tumor burden in Bcl-3-ablated lungs translatedinto significantly prolonged survival after tumor initiation." (PMID 27906182, 2016). "As BCL-3 is known to bind NF-κB p50 homodimers increasing its nuclear localisation, we investigated whether there was a correlation between levels of BCL-3 and NF-κB1 expression in the tumours." (PMID 26033966, 2016). "Cyld inhibits tumor cell proliferation by blocking Bcl3-dependent NFkB signaling." (PMID 26413810, 2015). "Also supporting this line of evidence is the finding that the tumor suppressor CYLD blocks cyclin D1 expression by inhibiting Bcl-3 signaling." (PMID 20731879, 2010). "Identification of Bcl-3 and other potential regulators for A20 in transformed tumour cells may help advance our understanding of the control of cell life and death induced by death factors such as TNF." (PMID 19826422, 2009). "N4BP2 and Bcl-3 mRNA levels appeared to be higher in tumor than in matched normal tissue." (PMID 17626640, 2007). "Since both Bcl3 and IL‐8 are IFNγ‐inducible genes that promote tumor cell proliferation, migration, and invasion, the positive regulation of IL‐8 by Bcl3 suggests that the Bcl3 oncogenic function in OC cells might be partly mediated by its upregulation of IL‐8." (PMID 37151134, 2023). "Thus, the high proportions of bcl-3−/− squamous lesions may reflect a requirement for Bcl-3 for optimal NF-κB signaling to support adenocarcinoma cell survival and tumor progression." (PMID 35681213, 2022). "Hence, BCL-3 may be particularly important as a survival factor in colorectal carcinogenesis in the context of stresses related to the tumour microenvironment." (PMID 26033966, 2016). "Evaluation of the nuclear fraction of Bcl-3 positive cells (estimated in percent), the nuclear intensity (scored 0–4) and the cytoplasmic intensity (scored 0–3) was possible in 264 of 270 (98%) tumour specimens and in 64 of 70 (91%) cases of normal colon tissue." (PMID 25929479, 2015). "Thus, the analyses of the BCL-3 expression status might be suitable for determining the prognosis of tumor progression and the disease course." (PMID 23578005, 2013). "With respect to BCL-3 staining, approximately one-third of patients were found to have high nuclear BCL-3 in tumor biopsies as assessed by immunostaining." (PMID 38420615, 2024). "RELB, NFKB1, BCL3, and FOXO3, found in NEAT1+ tumor cells, were closely related to the CSCs phenotype." (PMID 37430270, 2023). "We compared the transcriptome data between normal samples and GBM tumor samples, which indicated that ANXA1, PDPN, COL6A1, BCL3, RUNX1, and WWTR1 were upregulated and compared to normal samples, BCL11A was downregulated in GBM tumor samples." (PMID 37434432, 2023). "While we cannot rule out the possibility that the propensity toward squamous tumors in bcl-3−/− mice is due to overgrowth of less viable epithelial tumors, it is possible that strategies to reduce Bcl-3 activity may paradoxically select for a mesenchymal tumor phenotype." (PMID 35681213, 2022). "The spatial intratumoral heterogeneity of both IL6 and BCL3 expression was evaluated, corroborating IL6 upregulation throughout the tumor, while tumor and NTST showed a consistent increase of BCL3 expression relative to the healthy esophagus." (PMID 34422669, 2021). "In order to evaluate the spatial intratumoral pattern of IL6 and BCL3 expression in ESCC, we used three to six tumor biopsies from different regions of the tumoral mass and two fragments of non-tumoral surrounding tissue, from five patients with ESCC." (PMID 34422669, 2021).
tumor (continued). "Since Bcl-3 deficiency led to an enhanced effector but impaired memory CD8+ T cell response, it will be of great interest to investigate the role of Bcl-3 in CD8+ T cells in other acute and persistent infection and tumor models." (PMID 33508001, 2021). "We propose that BCL-3 acts as a driver of the stem cell phenotype in CRC cells, potentially promoting tumour cell plasticity and therapeutic resistance." (PMID 30792270, 2019). "Together, these data suggest that increased Bcl-3 expression in hepatocytes inhibits cell cycle progression and proliferation in HCC and tumor-surrounding tissue suppressing proliferation and hepatocarcinogenesis." (PMID 28915576, 2017). "Aukema and colleagues defined DHL as a neoplasm characterized by a MYC rearrangement combined with another genetic abnormality, such as BCL2, BCL3, BCL6, or other genes." (PMID 26515759, 2015). "miR-125b-5p targets multiple genes involved in the regulation of apoptosis including BAK1, BCL3, PUMA and STAT3, but depending on the cell type, miR-125b-5p contributes either to oncogenesis or to tumor suppression." (PMID 23527180, 2013). "Multiple lines of transcriptomic evidence in tumor-educated THP1 cells point to STAT3 pathway activation, including upregulation of canonical STAT3 targets (SOCS3, CISH, BCL3, JUNB, PIM1) and increased expression of STAT3-activating ligands (IL6, IL11, LIF, OSM) in response to TNBC contact." (PMID 41514627, 2025). "Targeting BCL3 is challenging, not least because of the multiplicity of its actions on transcriptional pathways and contradictory roles in some tumour models." (PMID 38195591, 2024). "Data from spleen show similar trend to breast between the untreated tumour and treated tissue, however the exception is that with the exception for PRF1 all other genes show higher expression in the verteporfin-PDT with BCL3 and CXCL1 showing the highest similar to that seen in breast tissue." (PMID 38022682, 2023). "Taken together, our results identify BCL-3 as a regulator of the cellular response to DNA damage and suggests that elevated BCL-3 expression, as observed in CRC, could increase resistance of tumour cells to DNA damaging agents including radiotherapy." (PMID 35468497, 2022). "Additionally, the tumor suppressive genes SAA1, VSIR, and BCL3 were also significantly upregulated in ACM samples." (PMID 36428692, 2022). "Additionally, tumor suppressive genes SAA1, VSIR, and BCL3 were also significantly upregulated in ACM samples." (PMID 36428692, 2022). "Moreover, Bcl-3 KD led to a >90% reduction in CSC frequency, as demonstrated by in vivo limited dilution assays, suggesting that Bcl-3 KD reduced tumor-initiating capacity." (PMID 32355204, 2020). "This was suggested to be mediated through TNF-α, as tumour burden was not increased in Bcl-3/TNF-α double KO mice." (PMID 31930327, 2020). "Targeting niche factors that promote stemness and plasticity, such as BMI-1 and BCL-3, may be an effective way to target CRC stem cells in primary tumours and prevent reversion of differentiated cells to LGR5+ CSCs." (PMID 30792270, 2019). "Considering the importance of Wnt/β-catenin and NF-κB crosstalk in cellular de-differentiation and tumour initiation in the intestine, surprisingly there have been no studies exploring the role of the NF-κB co-regulator BCL-3 in Wnt signalling in CRC." (PMID 30792270, 2019). "In accordance with this, several other studies confirm that increased tumour expression of p50 (and not p65) correlates with an increased expression of Bcl-3." (PMID 30205516, 2018). "Our study showed that Bcl-3 regulated the process of breastcancer pulmonary metastasis without affecting tumor proliferation." (PMID 27906182, 2016). "Next to BCL3, ERBB2/3 (Her2/Her3) are also downregulated upon miR-125b overexpression in human ovarian cancer cell lines, further demonstrating that this pathway is involved in the development of multiple tumor types in which miR-125b is tumor suppressive." (PMID 24774301, 2014).